EGFR (epidermal growth factor receptor)
Diseases named in the same sentence as EGFR in open-access papers (continued):
Sharing a sentence is not in itself a finding about the gene and the disease.
thyroid cancer (continued). "Subsequently, real-time RT-PCR analysis of TGFA and EGFR transcripts was performed on total RNA from 5 normal thyroid tissue samples from pathologies other than thyroid cancer and 23 PTC biopsies." (PMID 20877637, 2010). "EGFR has been shown to activate Met in lung and thyroid cancer cells as well as in the development of the kidney, hepatocytes, and retina." (PMID 20624308, 2010). "Given that doxorubicin is also a substrate of ABCG2, the inhibition of ABCG2 and the resultant decreased efflux of doxorubicin likely underlie the observed synergism, similar to the interaction seen with the EGFR inhibitor gefitinib and doxorubicin in thyroid cancer." (PMID 39033209, 2024). "Overall, our results suggest that EGFR expression levels are generally low in thyroid cancer, indicating that EGFR might be a poor therapeutic target for this patient group." (PMID 38076095, 2023). "Siglec-15 may enhance cancer cell invasion by promoting EGFR protein stability, as demonstrated in thyroid cancer." (PMID 37434177, 2023). "Stronger stainings were observed for CD44v6 than EGFR for all three thyroid cancer types." (PMID 38076095, 2023). "In addition, we measured EGFR protein expression also in thyroid carcinoma cells as other EGFR-positive tumor types for binding validation." (PMID 37048151, 2023). "It implies that EGFR may be used in thyroid cancer as a possible therapeutic agent in our set of population." (PMID 36245068, 2022). "This study aimed to analyze KRAS and EGFR mutation profiles in BRAF-V600E negative thyroid cancer samples." (PMID 36510281, 2022). "In addition, EGFR dependency correlated with the majority of genes from the first cluster in rhabdoid, gastric, neuroblastoma, breast, ovarian, and thyroid cancer cells." (PMID 36361596, 2022). "Nearly half of the BRAF-V600E negative thyroid carcinoma samples harbored either KRAS or EGFR mutations." (PMID 36510281, 2022). "We discovered that either KRAS or EGFR mutations can be found in nearly half of the BRAF negative thyroid carcinoma samples." (PMID 36510281, 2022). "We also observed that 45.7% of BRAF negative thyroid carcinoma samples had EGFR mutation, with 71.4% was found in papillary thyroid carcinoma." (PMID 36510281, 2022). "In addition, EGF/EGFR signal pathway plays a crucial role in the EMT progression of thyroid cancer cells." (PMID 34819077, 2021). "Similarly co-treatment of thyroid cancer cell lines with an EGFR inhibitor increased antitumor efficacy and suppressed resistance to the BRAF V600E inhibition." (PMID 34630336, 2021). "MiR-137 inhibits growth and invasion by targeting EGFR in thyroid cancer cells." (PMID 34819077, 2021). "This transcriptional control may provide thyroid cancer cells a growth advantage through the EGFR and β-catenin signaling pathways." (PMID 33203992, 2020). "Indeed, in FLCN-deficient thyroid cancer FTC-133 cells, dysregulation of RAB7 activity due to loss of FLCN determined slower EGFR degradation, increased EGFR signaling, and tumor growth." (PMID 31374919, 2019). "Epidermal growth factor receptor (EGFR), a tyrosine kinase receptor that can shuttle from the membrane to the nucleus, is an oncogene overexpressed in a variety of human cancers including thyroid cancer, and mediates cell proliferation via ERK and AKT signaling." (PMID 31312183, 2019). "A Phase I study investigated treatment with dabrafenib and lapatinib, the latter being a dual HER2/neu and epidermal-growth factor-receptor (EGFR) inhibitor, in patients with unresectable-radioiodine refractory thyroid cancer (ClinicalTrials.gov Identifier: NCT01947023)." (PMID 31762942, 2019). "In conclusion, our results demonstrate that EGCG could inhibit the growth and increase the apoptosis of human thyroid carcinoma cells via suppression of EGFR/RAS/RAF/MEK/ERK signaling pathway." (PMID 30858760, 2019). "The results indicate that EGCG could suppress the EGFR/RAS/RAF/MEK/ERK pathway in human thyroid carcinoma cells." (PMID 30858760, 2019).
thyroid cancer (continued). "EGCG could reduce the growth and increase the apoptosis of human thyroid carcinoma cells through suppressing the EGFR/RAS/RAF/MEK/ERK signaling pathway." (PMID 30858760, 2019). "At the beginning, the gene expression datasets from 1036 cancers from CCLE and 8215 tumors from TCGA were collected and analyzed, showing EGFR is predominantly overexpressed in thyroid cancers than other type of cancers (P = 0.017 in CCLE and P = 0.001 in TCGA)." (PMID 29849821, 2018). "Interestingly, the data from Croyle et. al. also suggest that thyroid cancer cells carrying RET fusion proteins are sensitive to EGFR inhibitors." (PMID 28460442, 2017). "Interestingly, the exposure of thyroid carcinoma cells to PLX4032 resulted in a rapid feedback activation of EGFR signaling with parallel activation of AKT phosphorylation." (PMID 29033690, 2017). "This study evaluated the hypothesis that feedback activation of EGFR signaling counteracts the cytostatic activity of vemurafenib (PLX4032) in BRAF V600E thyroid carcinoma cells." (PMID 29033690, 2017). "Cancer types with moderate to high frequencies of non-synonymous mutations in the EGFR pathway (> 50%) were combined for subsequent analysis: uterine corpus endometrial carcinoma (UCEC), skin cutaneous melanoma (SKCM), thyroid carcinoma (THCA) and colorectal adenocarcinoma (COAD)." (PMID 24152305, 2013). "G-protein-coupled estrogen receptor (GPER/GPR30) was reported to bind 17β-estradiol (E2), tamoxifen, and ICI 182,780 (fulvestrant) and promotes activation of epidermal growth factor receptor (EGFR)-mediated signaling in breast, endometrial and thyroid cancer cells." (PMID 23273253, 2012). "EGFR is also expressed in PTCs, and EGFR signaling may represent a molecular target in poorly differentiated thyroid carcinoma cells." (PMID 21364949, 2011). "Interference with EGFR activation has been previously considered in the therapy of thyroid cancers." (PMID 20877637, 2010). "Furthermore, Notarangelo and colleagues reported that the exposure of thyroid cancer cells to vemurafenib resulted in a rapid feedback activation of EGFR pathway, and dual EGFR and BRAF blockade induces suppression of ERK signaling, inhibition of cell proliferation, and synthetic lethality." (PMID 36624452, 2023). "This suggest that EGFR mutation profile in thyroid cancer should not be overlooked." (PMID 36510281, 2022). "Interestingly, coexistence mutations (both KRAS and EGFR mutations) were found in 1 of our BRAF negative thyroid carcinoma sample." (PMID 36510281, 2022). "These suggest that EGFR mutation profile in thyroid carcinoma should not be excluded." (PMID 36510281, 2022). "In thyroid cancer tissues, EGFR is highly expressed and related to lymph node metastasis, tumor histology, and clinical stage, which may indicate the aggressiveness of tumor, and its expression level is one of the important markers in clinical surgery and prognosis." (PMID 33055358, 2020). "However, recent research has shown that miR-137 was downregulated in thyroid cancer and inhibits proliferation and invasion by targeting EGFR, and it could act as a tumor suppressor in papillary thyroid carcinoma." (PMID 31032340, 2019). "Similarly, we found that, as compared to the other type of 7702 tumor tissues, the overall EGFR expression in 513 thyroid cancers is significantly overexpressed with 1.35-folds (thyroid cancers versus other cancers = 9.535 ± 0.049 versus 9.1838 ± 0.037 fluorescence intensity-log2, P = 0.001)." (PMID 29849821, 2018).
thyroid cancer (continued). "Furthermore, PTC clinical samples analyzed by real-time RT-PCR expressed EGFR transcript levels similar to those of 5 normal thyroid tissues from patients with pathologies other than thyroid cancer, whereas significantly elevated levels of TGFA transcripts were only present in PTCs." (PMID 20877637, 2010). "Thus, EGFR intervention alone seems to be insufficient in the treatment of thyroid cancer." (PMID 20877637, 2010). "Downregulation of RTN3 lead to stabilization of DHCR7 and elevate cholesterol concentration, activating EGFR/ERK pathway and contributes to progression of thyroid cancer, which can be rescued by HMG-CoA reductase inhibitor Simvastatin." (PMID 41813657, 2026). "Our findings support the efficacy of combined targeting of RET and EGFR in CCDC6-RET NSCLC and thyroid cancer cells, successfully preventing tumor cell growth under RET-resistant conditions." (PMID 40405293, 2025). "In the context of thyroid cancer, EGCG inhibits the growth and increases apoptosis of human thyroid carcinoma cells through the suppression of the EGFR/RAS/RAF/MEK/ERK signaling pathway." (PMID 40943396, 2025). "Lapatinib as a small molecule dual tyrosine kinase inhibitor of EGFR and HER-2 has been demonstrated the ability to prevent the rebound of the ERK signaling and sensitize BRAF-mutant thyroid cancer cells to RAF or MEK inhibitors." (PMID 38795180, 2024). "Sparing toxicities by reducing the affinity has been demonstrated for ICAM-1 specific CAR T cells (micromolar affinity) in thyroid cancer, as well as in HER2- and EGFR-specific CAR T cells in various solid cancer models including ovarian and prostate." (PMID 38962014, 2024). "The aim of this study was to explore EGFR, CD44v6 and BRAF as molecular targets in thyroid cancer by assessing patient samples from PFC, FTC and ATC, as well as in cultured thyroid cancer cell lines." (PMID 38076095, 2023). "Actually, inhibition of the BRAFV600E/MEK/ERK axis in thyroid cancer cells also results in reactivation of a variety of RTKs such as HER2/HER3, platelet-derived growth factor receptor-beta (PDGFRβ), and EGFR." (PMID 36624452, 2023). "The aim of this study was to assess the feasibility of targeted therapy of thyroid carcinoma, first exploring potential targets BRAF, EGFR and CD44v6 in patient material through immunohistochemistry and mutation analysis." (PMID 38076095, 2023). "The aim of this study was to assess the feasibility of targeted radionuclide therapy of thyroid carcinoma, first exploring potential targets BRAF, EGFR and CD44v6 in patient material through immunohistochemistry (IHC) and pyrosequencing." (PMID 38076095, 2023). "Vandetanib, an established inhibitor of VEGFR, EGFR, and RET kinases, is approved for the treatment of certain thyroid cancers." (PMID 34551970, 2022). "Lapatinib, a pan HER2/HER3/EGFR inhibitor, cooperated with vemurafenib to inhibit growth of BRAF-mutant thyroid cancer cell lines, an effect that was enhanced by YAP silencing." (PMID 36476495, 2022). "In a study, EGCG reduced the levels of phospho (p)-epidermal growth factor receptor (EGFR), H-RAS, p-RAF, p-MEK1/2, and p-ERK1/2 in human thyroid carcinoma cells." (PMID 36430487, 2022). "EGFR is activated by its ligand epidermal growth factor (EGF), which triggers a signal cascade, resulting in enhanced migration and invasion of thyroid cancer cells." (PMID 34819077, 2021). "EGCG reduced the protein levels of phospho (p)-epidermal growth factor receptor (EGFR), H-RAS, p-RAF, p-MEK1/2, and p-extracellular signal-regulated protein kinase 1/2 (ERK1/2) in human thyroid carcinoma cells." (PMID 30858760, 2019). "Epidermal growth factor receptor (EGFR)-dependent RET activation: an interaction between EGFR and RET was recently described, with EGFR reported to be over-expressed in thyroid cancer cells." (PMID 29057215, 2017).
thyroid cancer (continued). "In breast and thyroid cancer cells, as well as endometrial cells, GPER exerts its effects through the transactivation of the epidermal growth factor receptor (EGFR)." (PMID 28439256, 2017). "The HER/ErbB family of receptors including EGFR (HER1/ErbB1), HER2 (ErbB2), HER3 (ErbB3) and HER4 (ErbB4) plays a critical role in tumorigenesis including thyroid cancer." (PMID 27517321, 2016). "In the majority of anaplastic thyroid cancers EGFR is over-expressed and when activated by EGF a signaling cascade is activated that results in enhanced migration and invasiveness of thyroid cancer cells." (PMID 25058589, 2014). "Similarly, in thyroid carcinoma, we observed an interaction between ERBB3, a member of the epidermal growth factor receptor (EGFR) family of receptor tyrosine kinases, and four inhibitors (sapitinib, poziotinib, gefitinib, and dacomitinib)." (PMID 40258059, 2025). "Proteolytic cleavage of NrCAM at the cell surface of K1 cells results in the release of the extracellular domain of NrCAM, which activates EGFR signaling when presented in the culture medium to thyroid cancer IHH4 cells, suggesting that it binds in trans to EGFR at the cell surface." (PMID 39594667, 2024). "Furthermore, miR‐133a‐3p can regulate the PI3K/AKT/mTOR signaling pathway in thyroid cancer by modulating ZEB1‐AS1 and targeting LPAR3 and EGFR, inhibiting thyroid cancer cell proliferation while promoting cell death." (PMID 36305754, 2023). "EGFR-targeted treatment has been suggested as a treatment option in thyroid cancer, although the EGFR overexpression has not been widely investigated." (PMID 38076095, 2023). "Similarly, in lung cancer, the overexpression of ANXA8 activates the EGFR/AKT/mTOR signalling pathway to promote proliferation, while in thyroid cancer, increased ANXA1 promotes thyroid cancer proliferation by mediating IL-6/JAK2/STAT3." (PMID 36936694, 2023). "In this study, we found EGFR is overexpressed in thyroid cancer rather than the other types of cancer from CCLE and TCGA datasets." (PMID 29849821, 2018). "Interestingly, phosphorylation of other RTKs such as EGFR, ERBB2, and FLT-3 have recently been shown to be promoted when EcSOD is overexpressed in thyroid cancer cells." (PMID 29296173, 2017). "Here, we have also showed that EGFR expression is not up-regulated in PTC samples respect to normal thyroid tissues from pathologies other than thyroid cancer." (PMID 20877637, 2010). "However, prior to the current study, a functional TGFA/EGFR signaling loop has not been experimentally demonstrated in thyroid cancer." (PMID 20877637, 2010). "Further studies showed that NG2 was involved in maintaining the activities of multiple RTKs, such as EGFR, FGFR, HER2, IGF-1R, VEGFR and PDGFR, suggesting that these RTKs and their downstream signaling pathways may contribute to the resistance of BRAF-mutant thyroid cancer cells to BRAF inhibitor." (PMID 38795180, 2024).
cholangiocarcinoma (115 papers, 2008 to 2026). A carcinoma that arises from the intrahepatic biliary tree (intrahepatic cholangiocarcinoma) or from the junction, or adjacent to the junction, of the right and left hepatic ducts (hilar cholangiocarcinoma). "The activation of EGFR in O. felineus infection makes it a promising target for further study in the context of liver-fluke-associated cholangiocarcinoma (CCA) development and for early-stage diagnostics." (PMID 40732668, 2025). "Response-predicting EGFR mutation to EGFR TKIs involving exons 18, 19 and 21 had ever been described in a cohort of 22 cholangiocarcinoma patients." (PMID 33451059, 2021). "Signal transducer and activator of transcription 3 (STAT3) is a key mediator of the oncogenic effects caused by EGFR signaling in cholangiocarcinoma." (PMID 32365487, 2020). "Recent strategies examining EGFR-targeted therapy of cholangiocarcinoma have focused on EGFR tyrosine kinases related to the signaling of mutated and over-expressed EGFR." (PMID 22591401, 2012). "For example, the prevalence of EGFR mutations that we have found is in the range of that reported by other authors analyzing PC or cholangiocarcinoma." (PMID 21266046, 2011). "We have reported earlier that EGFR overexpression occurs in ∼20% of primary cholangiocarcinomas and is associated with tumour progression and poor outcome." (PMID 19319137, 2009). "Elevated vascular endothelial growth factor (VEGF) and epidermal growth factor receptor (EGFR) expressions are associated with the progression of cholangiocarcinoma." (PMID 19319137, 2009). "Somatic mutations of EGFR in the tyrosine kinase domain have been identified in a subgroup of patients with cholangiocarcinoma or gallbladder carcinoma." (PMID 19445727, 2009). "This study, analysing EGFR/VEGF/HER2 expression in the largest cohort of cholangiocarcinoma reported so far, showed for the first time that EGFR expression in IHCC is significantly associated with poor prognosis." (PMID 18087285, 2008). "Moreover, it was demonstrated that LPS induced a delayed (~6 hour) EGFR phosphorylation event in cholangiocarcinoma cells which was implicated in LPS-induced cell invasion." (PMID 25915403, 2015). "Overexpression, gene amplification, and mutation of epidermal growth factor receptor (EGFR) have all been associated with the tumorigenesis and progression of cholangiocarcinoma, and thus EGFR and its molecular transducers are thought to be ideal therapeutic targets for cholangiocarcinoma treatment." (PMID 22591401, 2012). "The incidence of EGFR mutations in cholangiocarcinoma is reported as 13.6–15.0%." (PMID 19319137, 2009). "Increased expression of EGFR and related receptors has been noted in O. viverrini-associated CCA, despite the fact that cholangiocarcinoma is characterized by the weak expression of HER2 and ERbB2." (PMID 40732668, 2025). "The objective response rate (ORR) was 3% (1/36) with one partial response (unconfirmed) in a BTC patient with KRASWT, EGFR-amplified cholangiocarcinoma." (PMID 40507311, 2025). "Elevated levels of EGFR and phosphorylated EGFR were observed in the bile duct epithelium of patients with cholangiocarcinoma, as well as in the bile duct epithelium of laboratory hamsters." (PMID 40732668, 2025). "The data obtained from the autopsy material confirmed increased EGFR expression in cholangiocarcinoma human samples." (PMID 40732668, 2025). "The specific staining results for the EGFR and EGFRp of the autopsy liver material from patients with cholangiocarcinoma (CCA) and those with CCA associated with Opisthorchis felineus infection (CCA + OF) revealed pronounced signals in the bile duct epithelium and fibrotic areas in both groups." (PMID 40732668, 2025). "It is interacting with EGFR in cholangiocarcinoma, contributing to the synergistic effect of their dual inhibition." (PMID 41271784, 2025).